ATG12 (autophagy related 12)
Description:
Ubiquitin-like protein involved in autophagy vesicles formation. Conjugation with ATG5 through a ubiquitin-like conjugating system involving also ATG7 as an E1-like activating enzyme and ATG10 as an E2-like conjugating enzyme, is essential for its function. The ATG12-ATG5 conjugate acts as an E3-like enzyme which is required for lipidation of ATG8 family proteins and their association to the vesicle membranes. As part of the ATG8 conjugation system with ATG5 and ATG16L1, required for recruitment of LRRK2 to stressed lysosomes and induction of LRRK2 kinase activity in response to lysosomal stress (By similarity). (Microbial infection) May act as a proviral factor. In association with ATG5, negatively regulates the innate antiviral immune response by impairing the type I IFN production pathway upon vesicular stomatitis virus (VSV) infection. Required for the translation of incoming hepatitis C virus (HCV) RNA and, thereby, for the initiation of HCV replication, but not required once infection is established.
Synonyms: APG12; APG12L; FBR93; HAPG12
Tractability: Antibody: UniProt places it where antibodies can reach, with high confidence. PROTAC: ubiquitination databases record sites on it; its protein half-life has been measured.
Gene: Protein-coding gene on chromosome 5 (115,828,200 to 115,841,837, reverse strand). Ensembl gene ENSG00000145782.
Subcellular location: Cytoplasm; Preautophagosomal structure membrane
Subcellular location (Human Protein Atlas): Nucleoplasm; Vesicles
Pathways (Reactome):
Autophagy: Macroautophagy; PINK1-PRKN Mediated Mitophagy; Receptor Mediated Mitophagy
Immune System: Negative regulators of DDX58/IFIH1 signaling
Gene Ontology:
Molecular function: protein binding; Atg8-family ligase activity; protein tag activity
Biological process: macroautophagy; negative regulation of defense response to virus; positive regulation of viral translation; regulation of autophagosome maturation; autophagosome assembly; autophagosome maturation; autophagy of mitochondrion; glycophagy; piecemeal microautophagy of the nucleus; autophagy; negative regulation of innate immune response; negative regulation of type I interferon production
Cellular component: Atg12-Atg5-Atg16 complex; autophagosome; phagophore assembly site membrane; autophagosome membrane; cytosol; phagocytic vesicle membrane; protein-containing complex; cytoplasm; membrane; transferase complex
Genetic constraint (gnomAD): Loss-of-function variants: 19 observed, 16.51 expected, observed/expected ratio (o/e) 1.15, 90% interval 0.8 to 1.67. The upper end of that interval is the gene's LOEUF score, 1.67, which puts it in group 6 of 6, group 1 being the genes least tolerant of losing a copy. Missense variants: 206 observed, 159.33 expected, observed/expected ratio (o/e) 1.29, 90% interval 1.15 to 1.45. Synonymous variants: 74 observed, 61.2 expected, observed/expected ratio (o/e) 1.21, 90% interval 1 to 1.47.
Homologues: Orthologues: chimpanzee ATG12 (99% identical), macaque ATG12 (96% identical), dog ATG12 (93% identical), guinea pig ATG12 (93% identical), pig ATG12 (92% identical), mouse Atg12 (89% identical), tropical clawed frog atg12 (67% identical), rat Atg12 (62% identical), zebrafish atg12 (58% identical), Drosophila melanogaster Atg12 (44% identical), Caenorhabditis elegans lgg-3 (29% identical).
Diseases named in the same sentence as ATG12 in open-access papers:
ATG12 is named in the same sentence as 119 diseases in open-access papers, as found by Europe PMC text mining. Sharing a sentence is not in itself a finding about the gene and the disease. The quoted sentences say what the papers report.
gastric cancer (27 papers, 2015 to 2025). A primary or metastatic malignant neoplasm involving the stomach. "Expression of ATG12 is associated with tumorigenesis and therapy resistance in colorectal and gastric cancer, but the mechanism of cancer-specific regulation of ATG12 has not been characterized." (PMID 39018396, 2024). "The association between miR-23b-3p and ATG12 has been discussed in gastric cancer cells; metabolic reprogramming has also been described in osteosarcoma." (PMID 36011286, 2022). "ATG12 is also a target of circPOFUT1 in regulating autophagy-related chemical resistance, and circPOFUT1 promotes ATG12 expression to regulate autophagy-associated chemoresistance by sponging miR-488-3p in gastric cancer." (PMID 38338839, 2024). "Bioinformatics analysis with starbase v2.0 revealed that MALAT1 formed complementary base pairing (two putative 7-mer complementary sequences) with miR-23b-3p, which has been shown to target ATG12 and regulates autophagy-associated chemoresistance in gastric cancer in the previous study." (PMID 29162158, 2017). "MALAT1 competitively sequestered miR-23b-3p and attenuated the inhibitory effect of miR-23b-3p on ATG12, thereby increasing the expression of ATG12 and promoting autophagy associated chemotherapy resistance of gastric cancer (GC) cells." (PMID 36829256, 2023). "NORAD then sponges miR-433-3p to increase the expression of autophagy-related genes ATG5 and ATG12, which helps in alleviating DNA damage and oxidative stress and eventually confers oxaliplatin resistance in gastric cancer (GC) cells." (PMID 35625948, 2022). "miR-23b-3p regulates the chemoresistance of gastric cancer cells by targeting autophagy-related gene 12 (ATG12) and HMGB2." (PMID 35159393, 2022). "A recent study stated that the lncRNA SNHG11 is involved in the progression of gastric cancer through regulation of the expression of catenin-β1 and autophagy-related 12 via miR-1276." (PMID 35845928, 2022). "By acting as a ceRNA for miR-23b-3p, MALAT1 suppresses miR-23b-3p-mediated ATG12 autophagy protein reduction, and induces gastric cancer cell autophagy and chemoresistance." (PMID 32174966, 2020). "lncRNA MALAT1 has also been found to confer to PTX resistance through targeting miR-23b-3p and ATG12 in gastric cancer cells." (PMID 32192494, 2020). "Recently, existing research has specified that Malat1 regulates autophagy through the sponge of mir-23-3p, which targets HMGB2 and ATG12 in gastric cancer." (PMID 31425535, 2019). "The knockdown of ATG12 impairs the effects of miR-1265 inhibition on gastric cancer progression and oncogenic autophagy." (PMID 31799196, 2019). "In addition, miR-23b-3p and miR-101 are able to reverse drug resistance of gastric cancer cells to multiple chemotherapeutics including VCR via targeting ATG12/HMGB2 as well as ANXA2." (PMID 32192494, 2020). "In addition, over-expression of miR-23b-3p, an autophagy-related modulator, has been found to sensitize gastric cancer cells to 5-FU by inhibiting expression of ATG12 and HMGB2." (PMID 32192494, 2020). "In addition, the competing endogenous RNAcircPOFUT1 can relieve the inhibitory effect of PLAG1 by binding to miR-488-3p, and PLAG1 regulates ATG12 expression to enhance tumor cell autophagy, thereby increasing the resistance of gastric cancer cells to cisplatin." (PMID 40276502, 2025). "Additionally, MALAT1 targets the PTX-resistant genes miR-23b-3p and ATG12 in gastric cancer cells." (PMID 38294554, 2024). "LncRNA MALAT1 could function as a sponge RNA of miR-23b-3p and conferred chemoresistance of gastric cancer cells through attenuating the inhibitory effects of miR-23b-3p on expression of autophagy related 12 (ATG12) and promote autophagy of gastric cancer cells." (PMID 32192494, 2020). "Additionally, oncogenic lncRNAs MALAT1 and PVT-1 could contribute to 5-FU resistance of gastric cancer by modulating expression of the miR-23b-3p/ATG12 axis and Bcl-2, respectively." (PMID 32192494, 2020).
gastric cancer (continued). "Qing‐Hua Cao et al24 also showed that up‐regulation of ATG12 was correlated with advanced TNM stage and clinical stage in gastric cancer." (PMID 33837652, 2021). "In gastric cancer, for example, exogenous overexpression of miR-23b-3p has been found to reverse DDP resistance by modulating expression of autophagy related 12 (ATG12) and high mobility group box 2 (HMGB2)." (PMID 32192494, 2020). "LncRNA MALAT1 attenuates the inhibitory effect of miR-23b-3p on target autophagy-related 12 (ATG12), leading to chemo-induced autophagy and chemoresistance in gastric cancer." (PMID 32429086, 2020). "Thus, circPOFUT1 promoted the proliferation, migration, invasion, and autophagy-related chemotherapy resistance of gastric cancer by activating PLAG1 and ATG12 through miR-488-3p binding." (PMID 40936702, 2025). "It has been reported that ATG2B, ATG5, ATG9B, ATG12, and ATG16L1 are closely related to gastric cancer (GC)." (PMID 37629426, 2023).
breast carcinoma (19 papers, 2011 to 2025). "Furthermore, higher ATG3, ATG5, and ATG12 expression levels are associated with a lower overall survival rate in breast cancer patients, indicating a predictive value of these genes." (PMID 40426890, 2025). "Furthermore, breast cancer database analysis of 35 genes in the canonical autophagy pathway shows that the upregulation of ATG12 and MAP1LC3B is associated with a low relapse-free survival probability of patients with ERBB2-positive breast tumors following treatments." (PMID 33801244, 2021). "Our previous study demonstrated that ERBB2 promotes autophagy by upregulating the essential autophagy pathway protein, ATG12 (autophagy-related 12), in breast cancer cells." (PMID 40395294, 2023). "Downregulation of ERBB2 or ATG12 increased cell death induced by chemotherapy drugs in ERBB2-positive breast cancer cells, whereas upregulation of ERBB2 or ATG12 decreased the cell death in ERBB2-negative breast cancer cells." (PMID 33801244, 2021). "Taken together, this study provides a novel approach for the treatment of ERBB2-positive breast cancer by targeting ATG12-dependent autophagy." (PMID 33801244, 2021). "Our bioinformatic analysis of published datasets shows that ERBB2 expression in human breast cancer tissues leads to upregulation of several essential autophagy genes including ATG12." (PMID 33801244, 2021). "In this study, we demonstrated that ERBB2 promotes autophagy by increasing the protein levels of the autophagy gene ATG12 (autophagy-related 12), contributing to the resistance of breast cancer cells to chemotherapy drugs or ERBB2-targeted antibody treatments." (PMID 33801244, 2021). "An analysis of the transcriptional status of ATG12 in > 50 breast cancer cell lines suggested that the ATG12 transcript is commonly upregulated in trastuzumab-unresponsive HER2-overexpressing breast cancer cells." (PMID 25053988, 2014). "ATG12 is differentially up-regulated in HER2 gene-amplified breast carcinoma cells that exhibitprimary (inherent) resistance to trastuzumab." (PMID 23307622, 2012). "To molecularlyestablish a causal role of ATG12-driven autophagy in the de novo resistance ofHER2 gene-amplified breast cancer cells to trastuzumab, we employed alentivirus-mediated stable knockdown of the ATG12 gene." (PMID 23307622, 2012). "Furthermore, the genetic knockdown of either PIK3C3 or ATG12 attenuated autophagy and re-sensitized breast cancer cells to doxorubicin." (PMID 38310598, 2024). "In human breast cancer cells, S100a9 could promote autophagy by upregulating the Beclin-1 and promoting the formation of Atg12-Atg5 and lysosome activation, thereby inducing cell death." (PMID 37723445, 2023). "In human breast cancer cells, S100a9 could promote autophagy and induce cell death by upregulating the expression of Beclin-1, as well as by promoting the formation of Atg12-Atg5 and lysosomal activation." (PMID 37723445, 2023). "This supports that autophagy promotion by upregulation of ATG12 and MAP1LC3B might cause treatment resistance of ERBB2-positive breast cancer, leading to a worse outcome for breast cancer patients." (PMID 33801244, 2021). "Furthermore, ERBB2-induced treatment resistance in breast cancer is contributed to at least by specific upregulation of ATG12 (autophagy-related 12) which promotes autophagy." (PMID 33801244, 2021). "Therefore, ERBB2 promotes ATG12 expression to increase autophagy leading to resistance of breast cancer cells to cell death induced by a chemotherapeutic drug or hypoxia." (PMID 33801244, 2021). "In support of this hypothesis, a study showed that ATG12 was upregulated in breast cancer cells and knockdown of the ATG12 gene fully suppressed the refractoriness of the cancer cells to treatment with molecularly targeted agents." (PMID 23765161, 2013).
breast carcinoma (continued). "Recent study revealed that ERBB2 promoted autophagy via upregulating the autophagy-related 12 (ATG12), which further induced resistance to ERBB2-targeted antibody lapatinib in breast cancer cells." (PMID 34252349, 2021). "In this work, Rg5 induced autophagy in breast cancer cells, which was demonstrated by the formation of autophagosomes observed by TEM, the upregulation of LC3-II, Beclin-1, Atg5, and Atg12 expression and the downregulation of p62 expression." (PMID 31963684, 2020). "Dormant breast cancer stem-like cells induced by farnesyl transferase inhibitors expressed high levels of autophagy markers, such as ATG5, ATG7, and ATG12." (PMID 26458814, 2015). "We also show that autophagy markers Atg5, Atg12, and LC3-B are expressed in these dormant stem cell-like breast cancer cells." (PMID 22046561, 2011). "One mechanism for the current clinical treatment of ERBB2-positive breast cancer with the ERBB2 antibody Herceptin/Trastuzumab (and possibly others) may be due to autophagy inhibition by the antibody-induced ERBB2 degradation and ATG12 downregulation." (PMID 33801244, 2021). "Finally, ERBB2 antibody treatment led to reduced expression of ATG12 and autophagy inhibition increasing drug or starvation-induced cell death in ERBB2-positive breast cancer cells." (PMID 33801244, 2021). "Recently, it has been reported that silibinin induced the LC3-II expression which closely correlate with the number of autophagosomes, as well as Atg12-Atg5 formation were increased, elevated expression of Beclin1 which was accompanied by a decreased level of Bcl-2 in MCF7 breast cancer cells." (PMID 26311737, 2015). "We analyzed the transcriptional profile of the ATG12 geneacross the Adai (GSE1090) gene expression dataset, which includes 56 breast cancer cell lines, andacross the Neve's gene expression data set, which includes 54 widely used breast cancer celllines." (PMID 23307622, 2012). "In this study, we demonstrate that ERBB2 promotes autophagy by upregulating ATG12 as well as other autophagy-related (ATG) proteins including ULK1, FIP200, ATG5, and ATG7, leading to breast cancer treatment resistance and worse outcome to patients with ERBB2-positive breast cancer." (PMID 33801244, 2021). "Furthermore, we analyzed 35 autophagy genes involved in the classical autophagy pathway and found that ATG12 and MAP1LC3B are the only genes which upregulation is correlated with worse RFS-based survival probability in patients with ERBB2-positive but not ERBB2-negative breast cancer." (PMID 33801244, 2021).
colorectal cancer (14 papers, 2018 to 2025). A primary or metastatic malignant neoplasm that affects the colon or rectum. "Single-nucleotide repeat shift mutations in ATG12 may be involved in the carcinogenesis and progression of gastric and colorectal cancer through the deregulation of autophagy." (PMID 36674743, 2023). "Functional studies in colorectal cancer cells revealed that LTR10 elements regulate tumor-specific expression of multiple genes associated with tumorigenesis, such as ATG12 and XRCC4." (PMID 39018396, 2024). "Knockdown of HOTAIR and ATG12, or overexpression of miR-93, suppressed autophagy and restored radiosensitivity in colorectal cancer cells." (PMID 33050642, 2020). "For example, overexpression of miR-214 enhances the sensitivity of radiotherapy in colorectal cancer by decreasing ATG12-induced autophagy." (PMID 31844419, 2019). "Additionally, CELF2 has been reported to increase ATG12 levels by modulating mRNA stability, thereby enhancing autophagic flux in colorectal cancer." (PMID 39715205, 2024). "Among these three miRNAs, we found miR-26a-5p was reported to regulate autophagy in colorectal cancer, osteosarcoma, hepatocellular carcinoma, glioma, and laryngeal squamous cell carcinoma by targeting ULK1/2, DAPK1, and ATG12." (PMID 34740994, 2021). "In colorectal cancer, lncRNA HOTAIR enhanced radioresistance via miR-93/ATG12 axis." (PMID 35600868, 2022). "Interestingly, the negative regulation of the JNK signaling pathway suppresses the ATG5 and ATG12 expression in hippocampus of epileptic rats, and the ERK promotes the expression of ATG5 in the human colorectal cancer cell lines." (PMID 35762728, 2022). "In colorectal cancer, HOTAIR upregulated ATG12 expression by sponging miR-93." (PMID 33050642, 2020).
hepatocellular carcinoma (11 papers, 2016 to 2025). A malignant tumor that arises from hepatocytes. "In human hepatocellular carcinoma cells, ELAVL1 regulates both autophagosome formation and autophagic flux via mediating translation of the autophagy-related genes (ATGs) ATG5 and ATG12." (PMID 38373797, 2024). "HuR has been shown to enhance the translation of ATG12 mRNA by binding to its 3’-UTR, thus facilitating autophagosome formation in hepatocellular carcinoma cells." (PMID 39715205, 2024). "For example, HAGLROS promotes proliferation, inhibits apoptosis and enhances autophagy by regulating the miR-5095/ATG12 axis and PI3K/AKT/mTOR signalling pathway in hepatocellular carcinoma." (PMID 35664787, 2022). "For example, miR-30a-3p inhibits hepatocellular carcinoma cell proliferation via the PI3K/AKT signaling pathway by targeting DNMT3a and suppresses renal cell carcinoma invasion and metastasis by targeting ATG12." (PMID 41361055, 2025).
melanoma (10 papers, 2018 to 2025). A malignant, usually aggressive tumor composed of atypical, neoplastic melanocytes. "Consistent with the results obtained with the inhibitors, silencing the expression of Atg7 and Atg12, essential components of the autophagy machinery, allowed melanoma cells to partially resist death and reduced LDH release after exposure to TRI-03." (PMID 40486906, 2025). "Knockout of ATG5 and ATG12 can reduce the colonization ability of melanoma cells in the lung and the invasion ability of gliomas, respectively." (PMID 34718338, 2021). "But overexpressed miR-23a in melanoma suppressed the invasive and migratory properties of melanoma cells by abrogating autophagy through directly targetting ATG12 via autophagy-mediated AMPK-RhoA pathway." (PMID 30266744, 2018). "In addition, miR-23a has been identified as a negative regulator of ATG12, while ATG12 regulated melanoma cell invasion and migration through AMP-activated protein kinase-RAS homolog family member A (AMPK-RhoA) pathway." (PMID 32340261, 2020). "In our experiment, autophagy was activated by CP in human melanoma cells, which was confirmed by the decreasing LC3-I/LC3-II ratio and the accumulation of Atg5/Atg12, as well as p62." (PMID 30149677, 2018). "Among them, we found several autophagy-related genes such as AMBRA1, ATG5, ATG12, ATG13 and ATG4B, which could be potentially downregulated in BRAFi-resistant melanoma cells." (PMID 30254376, 2019).